CSF1R (colony stimulating factor 1 receptor)
Diseases named in the same sentence as CSF1R in open-access papers (continued):
Sharing a sentence is not in itself a finding about the gene and the disease.
Obesity (21 papers, 2014 to 2025). Accumulation of substantial excess body fat. "Moreover, detection of differentially connected genes identified various genes previously identified to be associated with obesity in humans and rodents, e.g. CSF1R and MARC2." (PMID 25270054, 2014). "Studies have confirmed that the selective ablation of NK cells expressing CSF1R can prevent obesity and insulin resistance." (PMID 35187175, 2022). "Most Importantly, blocker that blocks parvalbumin and CSF1R interaction not only rescued M2 macrophage activation, insulin sensitivity and thermogenesis but also ameliorated obesity in mice." (PMID 35676256, 2022). "Other studies using CSF1R inhibitors to limit the development or progression of obesity show some limited effects, which are primarily explained by changes in the hypothalamus." (PMID 32007953, 2020). "In summary, in this study, six hub genes, including Mki67, Rac2, Itgb2, Emr1, Tyrobp and Csf1r were identified which could be used as therapeutic biomarkers for obesity." (PMID 36654490, 2023). "More importantly, serum concentrations of parvalbumin positively correlate with obesity in mouse and human, while treating mice with a recombinant parvalbumin blocker prevents its interaction with CSF1R and promotes M2 macrophage polarization and ameliorates diet-induced obesity." (PMID 35676256, 2022). "Moreover, targeting parvalbumin by a synthetic blocker that blocks the interaction between parvalbumin and colony stimulating factor 1 receptor (CSF1R) ameliorates diet-induced obesity in mice." (PMID 35676256, 2022). "Through comprehensive bioinformatics analyzing and experimental verification, our study found that three hub genes CSF1R, C1QC, and TYROBP were associated with immune cells infiltration, especially macrophages in adipose tissue under obesity induced IR condition." (PMID 33564304, 2021). "Moreover, obesity promotes the formation of a specific NK cell subpopulation through the IL-6/Stat3 signaling pathway, which expresses IL6Ra and Colony Stimulating Factor 1 Receptor (Csf1r), contributing to the onset of obesity, insulin resistance, and associated inflammation." (PMID 40564033, 2025). "This article revealed that CSF1R, C1QC, and TYROBP were potential hub genes associated with immune cells' infiltration and the function of proinflammation, especially adipose tissue macrophages, in the progression of obesity-induced diabetes or insulin-resistance." (PMID 33564304, 2021). "To test the possible role of SIRT6 on TNFα secretion after the onset of chronic inflammation during obesity, we developed a genetic mouse model for inducible SIRT6 deletion in macrophage colony-stimulating factor receptor 1 (Csf1r)–positive macrophages." (PMID 35150745, 2022). "PLX3397 is an oral tyrosine kinase inhibitor of CSF1R in macrophages, that was able to attenuate the negative effects of inflammation in several chronic conditions including fatty liver, obesity, diabetes and even cancer in preclinical studies." (PMID 38313276, 2024). "Oral consumption of PLX5662, a more brain-penetrant CSF-1R inhibitor than PLX3397, produces no alterations in consummatory behavior or weight gain in mice, while genetic activation of microglia by tumor necrosis factor a-induced protein 3 (TNFAIP3) causes obesity." (PMID 41228515, 2025).
prion disease (21 papers, 2014 to 2023). A transmissible disease that is caused by a protein that is able to induce abnormal folding of normal cellular proteins, leading to characteristic spongiform brain changes, which are associated with neuronal loss without an inflammatory response. "Using the ME7 model of prion disease we applied gain- or loss-of CSF1R function, as means to stimulate or inhibit microglial proliferation, respectively, to dissect the contribution of these cells to neurogenesis." (PMID 26541819, 2016). "In prion disease, a 10-fold expansion of the microglial population is observed, associated with the local proliferation of resident microglia driven through the CSF1R pathway." (PMID 24648328, 2014). "While other groups have demonstrated that microglia ablation in animal models of Alzheimer’s disease reduces the signs of disease, we have demonstrated that reducing microglia in the CNS of mice using the CSF-1R inhibitor PLX5622 accelerates prion disease." (PMID 36301895, 2022). "Recent studies have shown that many microglial receptors, such as CSF1R, PPARs-γ, and Tka-A, when activated or inhibited, can influence the phenotype of activated microglia in prion disease." (PMID 34751640, 2021). "In prion disease, the activation of CSF1R and the transcription factors PU.1 and CCAAT/enhancer-binding protein alpha (C/EBPα) modulate microglial proliferation." (PMID 34751640, 2021). "We also noted that 5 of these homeostatic genes typically decreased in MGnD microglia (Csf1r, Fcrls, Hexb, Jun and Tgfb1) were increased in prion disease over time, with two (Fcrls and Jun) upregulated at 100 dpi." (PMID 32381108, 2020). "Csf1r is activated together with Cebpa and Spi1 in prion diseases, consistent with a Motif 10 regulatory relationship including Cebpa-Spi1 and Csfr1 in the TRCs." (PMID 31959236, 2020). "Coincident with the induction of these potentially neuroprotective effects, treatment of mice with GW2580 or an anti-CSF1R blocking antibody, has been shown to slow the rate of neurodegeneration and extend survival times in mice with CNS prion disease." (PMID 33023255, 2020). "Previously, we found that prion disease was accelerated by ablation of microglia following treatment with the CSF-1R inhibitor PLX5622." (PMID 32381108, 2020). "Previously, we have demonstrated that microglial proliferation and associated phenotypic changes play a crucial role in the pathology of ME7-prion disease, and that this process is driven by the activation of CSF1R." (PMID 31504240, 2019). "The studies focused to targeting CSF1R suggest that microglial proliferation in prion disease, AD and ALS has a net detrimental contribution to the disease progression." (PMID 28690540, 2017). "The expression of CSF1 and its receptor CSF1R show similar patterns, appearing upregulated in prion disease, with the CCR2−/− background having a less pronounced effect." (PMID 24648328, 2014). "We recently showed that the proliferation of microglial cells during prion disease is controlled by the activity of the CSF1R pathway, and blocking this receptor has a beneficial effect by delaying the progression of the pathology." (PMID 24648328, 2014). "We previously demonstrated that the selective CSF1R inhibitor JNJ527 significantly blocked microglial proliferation in the ME7 mouse model of prion disease, and this has been detected by ex vivo autoradiography with the first generation TSPO ligand, [3H]PK11195." (PMID 37032328, 2023). "In mouse prion disease, CSF1R increases microglial activation and promotes neurodegeneration." (PMID 35062879, 2022). "Inhibition of Csf1r decreases microglial proliferation and delays neuronal damage in prion disease." (PMID 31959236, 2020). "We have previously demonstrated that the proliferation of microglial cells is a core component of the neuroinflammatory response in a model of prion disease, another chronic neurodegenerative disease, and is controlled by the activation of CSF1R (Gomez-Nicolaet al., 2013)." (PMID 26747862, 2016).
prion disease (continued). "These Csf1r‐dependent genes provide a short list of non‐redundant pathways that may be used by microglia to provide this neuroprotection and restrict the reactive astrocyte activation in prion disease." (PMID 35852018, 2022). "We further investigated this correlation and examined the effects of the inhibition of microglial proliferation by the selective blockade of the tyrosine kinase activity of CSF1R by GW2580 in macgreen mice with prion disease (ME7) or NBH controls." (PMID 26541819, 2016). "Depletion of microglia using CSF1R inhibitors confers deleterious effects in certain mouse models of PD (MPTP, human α-Syn AAV), LPS-induced sickness behavior, and prion disease." (PMID 36346385, 2022). "Our previous studies treating C57BL/10 mice with CSF-1R inhibitor PLX5622 beginning at either 14 or 80 dpi and continuing through terminal disease indicated that MG played a major role in prion disease survival following intracerebral inoculation of three distinct scrapie strains: RML, 22L and ME7." (PMID 36301895, 2022). "However, inhibition of CSF1R using PLX5622 (Plexxicon) impaired prion clearance and exacerbated prion pathology, suggesting that therapeutic strategies against prion disease should avoid simply eliminating or depleting microglia." (PMID 33672129, 2021). "It is possible that in the genetically modified mice with a constitutive loss of function of IL-34, CSF-1 compensates for the absence of IL-34 and drives proliferation through CSF1R to expand the microglial population in prion disease." (PMID 33162994, 2020). "Another study reported that the CSF1 receptor (CSF1R) inhibitor, GW2580, restrained microglial activation and proliferation in prion-infected mice and thereby attenuated neuronal damage and slowed down disease progression, indicating a deleterious effect of microglial activation in prion diseases." (PMID 33672129, 2021). "We blocked microglial proliferation for 4 weeks using the CSF1R tyrosine kinase inhibitor (GW2580), and demonstrated a reduction in neurogenesis that supports the hypothesis that microglia have a net pro-neurogenic effect during prion disease." (PMID 26541819, 2016).
Parkinson disease (20 papers, 2018 to 2026). A progressive degenerative disorder of the central nervous system characterized by loss of dopamine producing neurons in the substantia nigra and the presence of Lewy bodies in the substantia nigra and locus coeruleus. "We evaluate the use of colony stimulating factor 1 receptor (CSF1R) as a marker of microglial-associated neuroinflammation in deceased and living people with Parkinson’s disease." (PMID 40232849, 2025). "Heterozygous CSF1R variants were identified in patients with presentations similar to that of parkinsonism and bvFTD." (PMID 33802612, 2021). "This study underscores the significance of CSF1R imaging as a promising biomarker for brain immune function in Parkinson’s disease, which may be associated with cognitive and motor disease severity." (PMID 40232849, 2025). "Repolarizing the activated microglia into a homeostatic phenotype after CSF1R inhibition has also been observed in models of multiple sclerosis and Parkinson's disease." (PMID 39571180, 2025). "Sufficient removal of microglia by CSF1R inhibition was also previously shown in mouse models of Parkinson’s disease, 4-repeat tauopathies and during traumatic brain injury." (PMID 36829182, 2023). "Parkinsonism, other involuntary movements, and ataxia were present in 61%, 21%, and 27% of the previously reported group of 122 CSF1R-ALSP patients." (PMID 36559271, 2022). "Nevertheless, although an earlier age at onset, Parkinsonism and distinctive motor features may be more common in HDLS patients presenting AD neuropathology than AD cases carrying CSF1R TK mutations; the average disease duration for both these HDLS and AD patients was 7 years." (PMID 29544907, 2018). "The expression levels of APAF1 were correlated with scores for parkinsonism, as measured by the UPDRS and PDQ-39, while the expression levels of CSF1R were negatively correlated with scores for cognitive function, as measured by the MMSE and MoCA." (PMID 37108258, 2023). "Although direct evidence supporting enhanced CSF1R expression in activated microglia due to a higher demand for CSF1 is lacking, an overall CSF1R upregulation has been observed in mouse models of amyloidosis and neurotoxic models of Parkinson's disease (Murphy Jr." (PMID 39571180, 2025).
sarcoma (20 papers, 2017 to 2025). A usually aggressive malignant neoplasm of the soft tissue or bone. "An interventional phase Ib study (NCT04242238) evaluated the concurrent administration of DCC-3014 (i.e., CSF1R inhibitor) and avelumab (i.e., anti–PD-1 antibody) in patients with advanced high-grade sarcoma, to deplete immunosuppressive M2 macrophages." (PMID 41562047, 2025). "Specifically, the CSF1R inhibitor pexidartinib suppresses survival, migration, and M2 polarization of sarcoma TAMs in vitro and significantly inhibits osteosarcoma growth and metastatic spread in vivo, in a syngeneic murine model." (PMID 41562047, 2025). "Pexidartinib, a colony-stimulating factor 1 receptor (CSF-1R) inhibitor, is capable of being safely used with sirolimus to inhibit the growth of unresectable sarcoma and malignant peripheral nerve sheath tumors by decreasing the number of M2-like TAMs151." (PMID 38341519, 2024). "To evaluate the expression of targeted receptors in OS, we performed a pan-cancer analysis of The Cancer Genome Atlas (TCGA) database and found that FGFR1 and CSF1R were highly expressed in sarcomas." (PMID 37361567, 2023). "A majority of clinical trials studying CSF1R inhibitors are in very early clinical trial phases either as monotherapy or combination therapies for the treatment of relapsed/refractory sarcomas." (PMID 33381449, 2020). "In fact, blocking the CSF-1/CSF-1R axis results in a decrease in CD4+ Foxp3+ Tregs correlated with a reduction in tumor growth and enhances CD8+ T cell-mediated immunity in the sarcoma TME." (PMID 39457693, 2024). "Another study in sarcomas highlights the importance of targeting and reprogramming TAMs in the TME by investigating the impact of PLX3397, a potent CSF-1R inhibitor." (PMID 39457693, 2024). "Specifically, in sarcoma, the expression level of SMC4 is significantly correlated with monocyte markers CD14 and CSF1R, TAM marker CD80, and M1 macrophage marker PTGS2." (PMID 36719264, 2023). "For example, in a phase 1 clinical trial using a CSF1R small molecule inhibitor, pexidartinib (PLX3397) in pediatric patients with refractory solid tumors (including sarcomas) and leukemias showed tolerability, and the expansion cohort is still ongoing (NCT02390752)." (PMID 33381449, 2020). "Thus, antibody blockade of the CSF-1/CSF-1R axis suppresses RAE-1δ expression by TAMs in B16 S.C. tumors and autochthonous KP sarcomas." (PMID 29757143, 2018). "Among the drugs that inhibit the recruitment of TAMs, the CSF-1R inhibitor pexidartinib in clinical trials has excellent clinical benefits in solid tumors such as in tenosynovial giant-cell tumors (TGCT), unresectable sarcoma, and malignant peripheral nerve sheath tumors." (PMID 38787372, 2024).
atherosclerosis (18 papers, 2017 to 2025). A disease characterized by the build-up of fatty material and calcium deposition in the arterial wall resulting in partial or complete occlusion of the arterial lumen. "Recent studies have identified mutations in CSF1R linked to inflammation and immune disorders, including Sjögren’s syndrome and atherosclerosis." (PMID 40809841, 2025). "CYBB, HMOX1, IL1B, TYROBP, and CSF1R are key genes associated with ferroptosis, a form of cell death triggered by lipid metabolism abnormalities in the context of atherosclerosis." (PMID 40895546, 2025). "Atherosclerosis-associated monocytes/macrophages showed high expressions of Adgre1, Cd14, Fcgr1, and Csf1r and a low expression of Ly6c2." (PMID 33013913, 2020). "Since CSF1R promotes the release of pro-inflammatory chemokines, the finding that this gene is up-regulated while the miRNA targeting it is down-regulated in ES and AS plaques suggest the role of this miRNA-mRNA pair in atherosclerosis associated inflammation." (PMID 35488341, 2022). "Finally, CSF1R-associated signaling can also induce and reduce inflammation, can stimulate atherosclerosis and has anti-apoptotic characteristics." (PMID 34169069, 2021). "Bioinformatics analyse also support the significant involvement of CSF1R in atherosclerosis biological processes." (PMID 40809841, 2025). "The expression of the genes CYBB, FCER1G, TYROBP, IL10RA, and CSF1R is increased in both ANCA-associated vasculitis and atherosclerosis." (PMID 39702436, 2024). "Although CSF1R is a target in RA and atherosclerosis treatment, studies directly analyzing its role in the concomitant two diseases are limited." (PMID 35304503, 2022). "In mice, miR-155 represses colony stimulating factor 1 receptor (Csf1r) expression, reduces lesional macrophage content and proliferation and decreases lesion size at the early stage of atherosclerosis." (PMID 29899293, 2018). "According to the findings of our research, the genes CYBB, FCER1G, TYROBP, IL10RA, and CSF1R could represent relevant targets for the study and development of therapeutic strategies aimed at ANCA-associated vasculitis and atherosclerosis." (PMID 39702436, 2024). "Moreover, suppressing colony-stimulating factor-1 receptor (CSF1R) was reported to inhibit macrophage proliferation so as to slow down the progression of atherosclerosis." (PMID 35811739, 2022). "RUNX1, which may function as an important TF in the pathogenesis of patients with RA complicated with atherosclerosis, was predicted to participate in the regulation of the two hub genes CSF1R and ITGB2." (PMID 35304503, 2022). "Inhibiting CSF1R may aid in attenuating atherosclerosis advancement." (PMID 40809841, 2025). "Furthermore, CSF1R plays a crucial role in atherosclerosis pathogenesis." (PMID 40809841, 2025). "Thus, CSF1R plays a pivotal role in the development of atherosclerosis, but the specific downstream molecular pathways remain unclear due to the complexity of the mechanism and lack of research." (PMID 37810795, 2023). "The findings of further experiments and bioinformatic analyses revealed that CSF1R and PLAUR are important genes for the development of atherosclerosis." (PMID 37810795, 2023). "A total of 6 intersecting drugs targeting 3 genes, CSF1R, CTSS, and ITGB2, were selected as candidate druggable molecular targets for atherosclerosis." (PMID 35811739, 2022). "CSF1R and PLAUR are key hub genes of foam cells and may play an important role in the biological process of atherosclerosis." (PMID 37810795, 2023).